TBC1D3B (TBC1 domain family member 3B)
Description:
Acts as a GTPase activating protein for RAB5. Does not act on RAB4 or RAB11 (By similarity).
Synonyms: TBC1D3I; PRC17
Tractability: Antibody: UniProt places it where antibodies can reach, with medium confidence; its Gene Ontology location is reachable by antibodies, with medium confidence. PROTAC: UniProt records ubiquitination sites on it.
Gene: Protein-coding gene on chromosome 17 (36,165,683 to 36,176,636, reverse strand). Ensembl gene ENSG00000274808.
Subcellular location: Cell membrane
Subcellular location (Human Protein Atlas): Vesicles
Gene Ontology:
Molecular function: GTPase activator activity
Cellular component: endosome; membrane; plasma membrane
Genetic constraint (gnomAD): Loss-of-function variants: 0 observed, 6.57 expected, observed/expected ratio (o/e) 0, 90% interval 0 to 0.46. That is too few expected variants to judge how well the gene tolerates losing a copy. Missense variants: 8 observed, 81 expected, observed/expected ratio (o/e) 0.0988, 90% interval 0.057 to 0.18. Synonymous variants: 1 observed, 23.65 expected, observed/expected ratio (o/e) 0.0423, 90% interval 0.014 to 0.2.
Homologues: Orthologues: chimpanzee TBC1D3B (96% identical). Paralogues in human: TBC1D3G (99% identical), TBC1D3H (99% identical), TBC1D3D (99% identical), TBC1D3 (99% identical), TBC1D3C (99% identical), TBC1D3F (99% identical), TBC1D3I (99% identical), TBC1D3K (99% identical), TBC1D3L (99% identical), TBC1D3E (99% identical), TBC1D26 (30% identical), USP6NL (29% identical), and 33 more.
Diseases named in the same sentence as TBC1D3B in open-access papers:
TBC1D3B is named in the same sentence as 1 disease in open-access papers, as found by Europe PMC text mining. Sharing a sentence is not in itself a finding about the gene and the disease.
TBC1D3B shares sentences with these, for which no sentence is quoted: lung adenocarcinoma (1 paper).